MRC1 (mannose receptor C-type 1)
Description:
Mediates the endocytosis of glycoproteins by macrophages. Binds both sulfated and non-sulfated polysaccharide chains. (Microbial infection) Acts as a phagocytic receptor for bacteria, fungi and other pathogens. (Microbial infection) Acts as a receptor for Dengue virus envelope protein E. (Microbial infection) Interacts with Hepatitis B virus envelope protein.
Synonyms: MMR; hMR; CD206; CLEC13D; CLEC13DL; MRC1L1; bA541I19.1
Tractability: Small molecule: a structure with a bound ligand is known. Antibody: UniProt places it where antibodies can reach, with high confidence; its Gene Ontology location is reachable by antibodies, with high confidence; UniProt predicts a signal peptide or a membrane-spanning region. PROTAC: its protein half-life has been measured.
Gene: Protein-coding gene on chromosome 10 (17,809,014 to 17,911,164, forward strand). Ensembl gene ENSG00000260314.
Subcellular location: Endosome membrane; Cell membrane
Pathways (Reactome):
Disease: Dengue Virus Attachment and Entry; Modulation by Mtb of host immune system
Immune System: Cross-presentation of soluble exogenous antigens (endosomes)
Gene Ontology:
Molecular function: cargo receptor activity; protein binding; D-mannose binding; transmembrane signaling receptor activity
Biological process: receptor-mediated endocytosis
Cellular component: endosome membrane; plasma membrane; cell surface
Homologues: Orthologues: chimpanzee MRC1 (99% identical), macaque MRC1 (98% identical), rabbit MRC1 (89% identical), pig MRC1 (88% identical), dog MRC1 (86% identical), rat Mrc1 (83% identical), guinea pig MRC1 (83% identical), mouse Mrc1 (82% identical), tropical clawed frog mrc1 (55% identical), zebrafish mrc1a (49% identical), zebrafish mrc1b (39% identical). Paralogues in human: MRC2 (33% identical), PLA2R1 (28% identical), LY75 (27% identical), CD302 (4% identical).
Diseases named in the same sentence as MRC1 in open-access papers:
MRC1 is named in the same sentence as 466 diseases in open-access papers, as found by Europe PMC text mining. Sharing a sentence is not in itself a finding about the gene and the disease. The quoted sentences say what the papers report.
breast cancer (124 papers, 2012 to 2026). A primary or metastatic malignant neoplasm involving the breast. "Similarly, other downregulated genes (Fabp4, Mrc1, Lpl, Cd209d, and Cd209a) were also found to be involved in breast cancer and may be associated with bone metastases." (PMID 35388653, 2022). "In breast cancer, TAp73 expression is negatively correlated with the accumulation of pro-tumorigenic MRC1+ macrophages in patient samples." (PMID 40612672, 2025). "For example, MRC1(+)TIE2(Hi)CXCR4(Hi) macrophages present in human breast carcinomas and bone metastases accumulate around blood vessels in tumors after chemotherapy, where they promote tumor revascularization and relapse." (PMID 39516356, 2024). "Using the cancer genome atlas database we also found that increased gene expression of Igf-1, Igf-2, and the M2-like macrophage markers cd163 and mrc1 positively correlates with reduced survival in breast cancer patients." (PMID 29367764, 2018). "A similar activation signature that was distinct from alternative macrophage activation (with the notable exception of MRC1) was recently reported for TAMs in a breast cancer model." (PMID 25702581, 2015). "A perivascular MRC1-expressing TAM subpopulation in patients with breast cancer has been shown to be crucial for tumor relapse after chemotherapy, suggesting that the spatial patterns we observed in murine models might be conserved in human tumors." (PMID 29991530, 2018). "Additionally, TEMs also show a unique surface marker profile consisting of Tlr4, Mrc1, Il4ra, and CD163, which differentiate them from TAMs in murine mammary tumors." (PMID 33968034, 2021). "4T1-GFP mammary carcinoma cells do not express the mannose receptor MRC1 and, as expected, treatment with mannosylated clodronate liposomes at both concentrations (1:50 and 1:100 dilution) did not affect viability of 4T1-GFP cells." (PMID 29164051, 2017). "Hughes R. and others demonstrated that MRC1+TIE2HiCXCR4Hi TAMs accumulate around blood vessels in both LLC1 tumors and orthotopic 4T1 and MMTV-PyMT implants after chemotherapeutic impact, as well as in human breast carcinomas after neoadjuvant treatment with paclitaxel." (PMID 39516356, 2024).
colorectal cancer (109 papers, 2002 to 2025). A primary or metastatic malignant neoplasm that affects the colon or rectum. "In colorectal cancer liver metastases, highly metabolically active MRC1+CCL18+ M2 macrophages have been identified and are associated with poor response to neoadjuvant chemotherapy." (PMID 40612672, 2025). "For example, MRC1+ CCL18+ macrophages in colorectal cancer show enrichment in oxidative phosphorylation, while macrophages in liver metastasis primarily rely on amino acid metabolism." (PMID 39015576, 2024). "In addition, compared with neighboring tissues, CTLA4+CD8+T, SPP1+ macrophages and MRC1(CD206)+ CCL18+ macrophages were also enriched in tumor tissues in the samples of colorectal cancer liver metastasis." (PMID 38279145, 2024). "Reduced circPCLE1 expression inhibits M2 macrophage markers (IL-10, MRC1), glucose consumption, and cell proliferation in colorectal cancer, while increasing the proportion of M1 macrophage markers (TNF-, IL-6) and decreasing the CD206+ and CD168+ macrophages." (PMID 38523627, 2024). "In colorectal cancer, SPP1+ macrophages highly express complement component 1C chain (C1QC), mannose receptor C type 1 (MRC1), signal transducer and activator of transcription 1 (STAT1), and peroxisome proliferator-activated receptor gamma (PPARG), which are associated with macrophage polarization." (PMID 38919629, 2024).
ovarian carcinoma (72 papers, 2008 to 2025). A malignant neoplasm originating from the surface ovarian epithelium. "Consistent with their tumor-promoting functions, TAM expressing high levels of the scavenger receptor CD163 and the mannose receptor CD206/MRC1 are immunosuppressive and predictive of an early relapse of ovarian carcinoma after first-line therapy (13, –15)." (PMID 29141914, 2018). "We have previously shown that TAM in ovarian cancer ascites can be stratified into subsets based on the expression of the surface markers CD163 and CD206 (encoded by the MRC1 gene), both of which show a high degree of variance among patients (1–94% CD163+ or CD206+ of the CD14+ TAM population)." (PMID 29141914, 2018). "CD163 and CD206/MRC1, which are strongly expressed on TAMs, are receptors for immunosuppressive molecules and predict the early recurrence of ovarian cancer." (PMID 32774171, 2020). "CD163 and MRC1 mRNA expression also correlated with the ascites levels of IL-10, which is prognostic of a short RFS of ovarian cancer." (PMID 29141914, 2018). "Importantly, recent single cell RNA sequence data confirmed expression of CD16 (FCGR3A), CD206 (MRC1), CD163, and CRIg (VSIG4) in macrophages from both peritoneal fluid at steady state and ovarian cancer ascites." (PMID 37180125, 2023).
glioma (71 papers, 2004 to 2026). A benign or malignant brain and spinal cord tumor that arises from glial cells (astrocytes, oligodendrocytes, ependymal cells). "To further demonstrate the specificity and efficacy of Mann2-DTPA-Gd to CD206+ TAMs, we performed MR imaging of glioma using Mrc1+/- mice, Mrc1-/- mice, and Mrc1+/+ mice with competition using D-mannose." (PMID 39776805, 2025). "This study demonstrated that inhibition of miR-454-3p in glioma cells promoted M2 macrophage polarization, corresponding to elevated expression of II1b, Cd86, and Nos2, and reduced expression of Cd163, Ym1 and Mrc1 in macrophages." (PMID 33363140, 2020). "Markers associated with an anti-inflammatory response, such as Arg1, Mrc1 and Il4ra24, are expressed at a higher level in glioma-infiltrating cells, as compared to blood-derived cells." (PMID 32555306, 2020). "The number of M2 MRC1‐positive macrophages significantly correlated with vessel diameter in accordance with the WHO glioma grade classification." (PMID 29038312, 2017). "We showed that CD206-targeted MRI can detect CD206+ TAMs, differentiate Mrc1+/+, Mrc1+/-, and Mrc1-/- mice, and track treatment changes of CD206+ TAMs treated by D-mannose in a mouse model of glioma." (PMID 39776805, 2025). "Interestingly, the number of MRC1‐positive macrophages significantly correlates with blood vessel diameter increase during glioma growth, suggesting a direct effect of the switch in macrophage polarization on blood vessel morphology." (PMID 29038312, 2017). "Given the significant correlation between M2 MRC1‐positive macrophages and blood vessel dilation during glioma growth, and the pronounced M2 accumulation around blood vessels, we searched for an M2‐derived factor that might mediate the effects." (PMID 29038312, 2017). "In vivo specificity and efficacy of the agents were evaluated by MRI in a subcutaneous wound healing model and experimental glioma with Mrc1+/+ without and with D-mannose treatment, Mrc1+/-, and Mrc1-/- mice, and in stroke." (PMID 39776805, 2025). "In the context of a high-grade brain tumor model where glioma-associated macrophages/microglia (GAMs) were M2 polarized, CSF1R inhibitors were found to decrease expression of M2 markers in GAMs such as Arg1 and Mrc1 (CD206) without influencing their numbers." (PMID 34281564, 2021). "CLIC4 expression levels were positively correlated with specific markers of macrophages (CD80, CD86, MRC1), neutrophils (FCGR3A, FCGR3B), eosinophils (SIGLEC8, IL3RA), T cells (CD3D, CD4), CD8+ T cells (CD8A, CD8D), NK cells (NCAM1), and B cells (CD19) in glioma." (PMID 39595145, 2024).
colon carcinoma (65 papers, 2009 to 2026). "In the current study, we demonstrated that VIP antagonist enhanced M1 markers TNF-α, iNOS, and CXCL10, reduced Mrc-1 mRNA expression, and increased phagocytic ability against CT26 colon cancer cells in mouse macrophage RAW264.7 cells incubated with CT26-CM." (PMID 36650220, 2023). "The expression of M2-like macrophage markers Arg1, MRC1 and IL-10, CCL17, and CCL22 were down-regulated, and the expression of M1-like macrophage markers iNOS, IL-12, and TNFa were induced by cetuximab in modeled TAMs, treated with CM of colon cancer cells in vitro." (PMID 34209679, 2021).
Stroke (59 papers, 2015 to 2026). Sudden impairment of blood flow to a part of the brain due to occlusion or rupture of an artery to the brain. "In line with a progressive elevation of the anti-inflammatory/neuroprotective response of microglia and infiltrating macrophages in the post stroke period, at 7 days Mrc1, Tgfb1 and Trem2 transcripts also significantly increased." (PMID 33246465, 2020).
lung carcinoma (52 papers, 2014 to 2025). "For example, the P453Q variant in MRC1 had a LOR of -7.47 (95% CI: -2.52–-10.44), suggesting an inhibitory effect against lung cancer." (PMID 39172974, 2024). "Alternatively activated macrophages expressing MRC1, TIE2 and CXCR4 also stimulate tumor relapse in a model with Lewis lung carcinoma cells and promote angiogenesis via VEGFA secretion." (PMID 38532508, 2024). "In mouse models bearing lung cancer, melittin inhibited tumor growth and increased TAMs M1/M2 ratio by selectively decreasing CD206+ M2-like TAMs, VEGF, CD31 (angiogenesis marker), and Mrc1/CD206 protein and gene expression in tumor cells." (PMID 37513529, 2023). "MARCO+ macrophages cultured with lung cancer cell lines displayed decreased expression of pro-inflammatory cytokines (TNFa, IL1B and IL12B) and increased expression of anti-inflammatory molecules (IL10, MRC1, COX2, TIMP1, and FIZZ1)." (PMID 36686729, 2022). "(ii) The conserved upregulation of TAM-promoting genes (e.g., Arg1, Mrc1 and F13a1) across tumour types suggests that SFV-based therapies could have broader applicability in reprogramming TAMs in other malignancies, such as glioblastoma or lung cancer." (PMID 40547518, 2025). "Interestingly, comparing to the MDMs from HCs, some cases of lung cancer patients’ MDMs showed MPE-Mφ-like patterns on elevating expression levels of CXCL10, CCL18, and MRC1, may indicate the local and systemic effects of the tumor microenvironment." (PMID 33175182, 2021).
melanoma (51 papers, 2015 to 2025). A malignant, usually aggressive tumor composed of atypical, neoplastic melanocytes. "In preclinical models of melanoma, 2-DG decreases TAM expression of Arg1, Fizz, Mrc1 (encoding CD206), and Vegf, indicating that 2-DG diminishes immunosuppression within the TME." (PMID 38226622, 2024). "Moreover, the high expression of MRC1 and high proportion of M2 macrophages but not of activated DCs significantly correlated with better overall survival in melanoma patients." (PMID 35503656, 2022).
Obesity (51 papers, 2011 to 2026). Accumulation of substantial excess body fat. "Notably, Mrc1 deficiency appears to counterbalance this effect, limiting the immunometabolic response observed during obesity." (PMID 36557243, 2022). "In addition, Mrc1 deficiency impacts the BM cell profile and reduces the number of activated immune cells in circulation and their infiltration in tissues, thus dampening obesity development." (PMID 36557243, 2022). "In conclusion, we have shown that, during the onset of obesity, Mrc1 impacts hematopoietic stem cell differentiation and release." (PMID 36557243, 2022). "Parallel to systemic metabolic alterations and hematopoietic cell proliferation, high-fat diet (HFD) feeding increases the expression of Mrc1 in sinusoidal ECs, thus calling for the investigation of its role in bone marrow cell reprogramming and the metabolic profile during obesity." (PMID 36557243, 2022). "Mrc1 deficiency is associated with a decrease in circulating neutrophils and pro-inflammatory CCR2+ monocytes and low infiltration of these cells into tissues, against a background of increased presence of adipocytes in the BM in obese mice (Mrc1-/-) (slowing the development of obesity)." (PMID 37569635, 2023). "During the early stages of obesity, secreted CTRP6 may contribute to a pro-inflammatory environment by enhancing TNF-α secretion and NO production from adjacent resident macrophages, while concurrently suppressing their M2-associated gene expression, including Mrc1 and Pparg." (PMID 41159061, 2025). "Expression of Mrc1, coding for the M2-like macrophage marker CD206, is maintained during obesity, WL, and WC." (PMID 35618862, 2022). "On the other hand, the mRNA levels of CD206, IL-10, Fizz1, Mrc1 and PPARγ were reduced in obesity group, and PDX treatment significantly increased the levels of CD206, Fizz1 and PPARγ in epididymal adipose tissue." (PMID 35185543, 2021). "Collectively, the dramatic suppression of MRC1 and the upregulation of TNF-α production induced by CTRP6 could aggravate the characteristic low-grade inflammation that persists chronically in obesity." (PMID 41159061, 2025). "Altogether, the decreased presence of macrophages, the combination of reduced levels of myeloid precursors and mature cells, and the increased adipocyte content suggest that the lack of Mrc1 could promote a medullary rewiring in mice with diet-induced obesity." (PMID 36557243, 2022).
colitis (45 papers, 2016 to 2025). Inflammation of the colon. "In a previous study, a SERM was shown to ameliorate DSS-induced colitis via the promotion of Mrc-1 positive anti-inflammatory macrophage phenotype and regulation of pro-inflammatory cytokine and chemokine expression." (PMID 38916850, 2024). "Indeed, M2-associated genes (Arg1, IL-10, Fizz1, and Mrc1) were increased and M1-associated genes (IL-1β, IL-6, IL-12, and TNF-α) were decreased in colons of DSS colitis miR-155−/− mice." (PMID 29774026, 2018). "Nevertheless, BM-MSC treatments downregulated Nos2, Arg1, Gata3, Mrc1 and Hmox1 which were upregulated in Winnie mice and IBD patients; but are reportedly also upregulated by MSCs in chemical models of colitis." (PMID 38503815, 2024). "Genes representative of anti-inflammatory macrophage polarization (Mrc1, Hmox1, Arg1 and Chi3l3) were either unchanged or downregulated by MSC treatments in contrast to some reports in acute chemically-induced colitis models." (PMID 38503815, 2024). "We utilized a dextran sodium sulfate (DSS)-induced colitis model in FVB/n mice to demonstrate the effects of orally administered SERM2 on the clinical status of the mice and the histopathological changes in the colon, as well as proportion of Mrc-1 positive macrophages." (PMID 31226730, 2019).
pancreatic cancer (42 papers, 2016 to 2025). "In addition, the expression of the TAM-related biomarkers MRC1/CD206 and CD163 was higher than that in normal human pancreatic tissue, indicating that TAMs are highly infiltrative in pancreatic cancer." (PMID 36324684, 2022). "Moreover, SLC40A1 expression positively correlates with the expression of TAM genes (CD68, MRC1, IL10, CSF1, and CSF1R) in pancreatic tumors." (PMID 36333531, 2022).
pulmonary fibrosis (32 papers, 2015 to 2025). Chronic progressive interstitial lung disorder characterized by the replacement of the lung tissue by connective tissue, leading to progressive dyspnea, respiratory failure, or right heart failure. "PDT-LD4 exerts anti-fibrotic effects in bleomycin-induced pulmonary fibrosis through multiple mechanisms including anti-inflammation, anti-oxidation and anti-fibrosis, which may be related to the regulation of MRC1." (PMID 41394130, 2025). "The macrophage mannose receptor (MRC1, also known as CD206) has emerged as a protein of significant interest in the context of fibrotic diseases, including pulmonary fibrosis." (PMID 41394130, 2025). "Proteomic profiling identified macrophage mannose receptor (MRC1) as a differentially expressed protein, whose BLM-induced upregulation was reversed by PDT-LD4, suggesting that the regulation of pulmonary fibrosis (PF) may involve the modulation of MRC1." (PMID 41394130, 2025). "Nonetheless, the expression of CSF1R, MRC1, and FN1 exhibited a significant reduction following SC-43 treatment, implying that SC-43 may inhibit the CSF1R/STAT3 signaling pathway and diminish the expression of fibrotic genes within macrophages in vivo during the pulmonary fibrosis progression." (PMID 37291088, 2023).
glioblastoma (30 papers, 2014 to 2025). The most malignant astrocytic tumor (WHO grade IV). "For example, using mouse glioblastoma as an experimental object, researchers used CSF-1R inhibitors to reduce the expression of Arg1 (arginase 1) and Mrc1 (CD206, mannose receptor) genes in the TME, thereby inhibiting tumor growth and metastasis." (PMID 34683963, 2021).
Sepsis (29 papers, 2012 to 2025). Sepsis is defined as life-threatening organ dysfunction caused by a dysregulated host response to infection. "Concordantly, increased expression of Arg1, Mrc1 and Retnla (encoding Fizz-1) was found in a CD11b+ macrophage-enriched population isolated from the lungs of sepsis-surviving mice by day 10 after CLP." (PMID 28374774, 2017). "Neutrophils are crucial in the immune response during sepsis, and the ceRNA network involving AC145207.5 and miR-23a-3p modulates MRC1 expression." (PMID 39216003, 2024). "Compared with classical blood biomarkers of systemic inflammation (e.g., CRP), the proteins detected in this study, including haptoglobin, vWF, MBL1, MRC1, sCD14, and LBP, showed a very early response to infection, indicating their potential in serving as new early markers of infection or sepsis." (PMID 31803186, 2019).
prostate carcinoma (28 papers, 2014 to 2025). A carcinoma that arises from epithelial cells of the prostate gland. "Androgen deprivation therapy (ADT) induces the accumulation of TAMs around blood vessels and increases the expression of markers of a protumor phenotype, including folate receptor-beta (FR-β), MRC1 (CD206), CD169 and VISTA, in PvTAMs in human and mouse prostate cancers." (PMID 39516356, 2024).